Y_RNA (Y RNA )
Gene: Miscellaneous RNA gene on chromosome 1 (32,639,951 to 32,640,052, forward strand). Ensembl gene ENSG00000200591.
Homologues: Orthologues: chimpanzee Y_RNA (100% identical), macaque Y_RNA (97% identical). Paralogues in human: RNY3 (91% identical), Y_RNA (90% identical), Y_RNA (89% identical), Y_RNA (88% identical), RNY3P1 (87% identical), Y_RNA (87% identical), Y_RNA (86% identical), Y_RNA (85% identical), Y_RNA (84% identical), RNY3P14 (83% identical), RNY3P16 (83% identical), RNY3P4 (83% identical), and 96 more.